ST7L (suppression of tumorigenicity 7 like)
Synonyms: ST7R; FLJ20284; STLR; FAM4B
Tractability: Antibody: UniProt predicts a signal peptide or a membrane-spanning region. PROTAC: ubiquitination databases record sites on it.
Gene: Protein-coding gene on chromosome 1 (112,523,487 to 112,620,825, reverse strand). Ensembl gene ENSG00000007341.
Subcellular location: Membrane
Subcellular location (Human Protein Atlas): Centrosome
Gene Ontology:
Biological process: negative regulation of cell growth
Cellular component: membrane
Genetic constraint (gnomAD): Loss-of-function variants: 39 observed, 52.94 expected, observed/expected ratio (o/e) 0.74, 90% interval 0.57 to 0.96. The upper end of that interval is the gene's LOEUF score, 0.96, which puts it in group 4 of 6, group 1 being the genes least tolerant of losing a copy. Missense variants: 422 observed, 535.32 expected, observed/expected ratio (o/e) 0.79, 90% interval 0.73 to 0.85. Synonymous variants: 177 observed, 197.94 expected, observed/expected ratio (o/e) 0.89, 90% interval 0.79 to 1.01.
Homologues: Orthologues: chimpanzee ST7L (96% identical), pig ST7L (91% identical), dog ST7L (91% identical), guinea pig ST7L (88% identical), rat St7l (87% identical), mouse St7l (86% identical), macaque ST7L (84% identical), tropical clawed frog st7l (71% identical), zebrafish st7l (70% identical), Drosophila melanogaster CG3634 (59% identical), Caenorhabditis elegans F11A10.5 (45% identical). Paralogues in human: ST7 (72% identical).
Diseases named in the same sentence as ST7L in open-access papers:
ST7L is named in the same sentence as 18 diseases in open-access papers, as found by Europe PMC text mining. Sharing a sentence is not in itself a finding about the gene and the disease. The quoted sentences say what the papers report.
hepatocellular carcinoma (6 papers, 2017 to 2025). A malignant tumor that arises from hepatocytes. "Overexpression of lncRNA MIR31HG decreased the expression of miR-575 by targeting ST7L, which acted as a tumor suppressor in hepatocellular carcinoma." (PMID 36162992, 2022). "For example, it is reported that overexpression of MIR31HG significantly decreased the expression of miR-575, enhanced the suppression of tumorigenicity 7 like (ST7L) in hepatocellular carcinoma (HCC)." (PMID 33334367, 2020). "Although miR-575 has not been previously linked to PDAC, it has been implicated in development of other gastrointestinal cancers, such as gastric cancer via inhibition of PTEN, biliary cancer via inhibition of p27Kip1, and hepatocellular carcinoma via inhibition of ST7L." (PMID 34680317, 2021). "In addition, MIR31HG inhibited hepatocellular carcinoma (HCC) proliferation and metastasis by directly binding miR-575 to positively modulate the expression of ST7L." (PMID 37636269, 2023).
cervical cancer (2 papers, 2021 to 2023). A primary or metastatic malignant neoplasm involving the cervix. "MicroRNA-378 was found to be an onco-miRNA, and its upregulation was reported in cervical cancers by targeting ST7L/Wnt/β-catenin pathways." (PMID 37240034, 2023). "ElevatedmiR-378a expression has also been reported in cervical cancer tissues and cell lines, and may act through the ST7L/Wnt/β-catenin signaling pathway." (PMID 34837692, 2021).
pancreatic cancer (2 papers, 2023 to 2026). "Overall, this study implicates functional genes in pancreatic cancer risk and characterizes a regulatory variant that modulates ST7L expression, advancing the interpretation of GWAS findings and understanding of pancreatic cancer biology." (PMID 41824785, 2026). "Nevertheless, so far, miR-331-3p is upregulated in pancreatic cancer cells, where it induces resistance to gemcitabine by activating the Wnt/β-catenin signaling through ST7L." (PMID 37993925, 2023). "Elevated ST7L dampens AKT/β-catenin signaling and suppresses pancreatic cancer cell proliferation, consistent with the protective association." (PMID 41824785, 2026).
acute myeloid leukemia (1 paper, 2018). Acute myeloid leukemia (AML) is a group of neoplasms arising from precursor cells committed to the myeloid cell-line differentiation. "In acute myeloid leukemia and glioblastoma, miR-24-3p promoted cell proliferation and metastasis by decreasing MAPK phosphatase-7 and ST7L expression." (PMID 29850625, 2018).
leukoplakia (1 paper, 2025). A white patch or plaque on a mucous membrane that cannot be characterized clinically or pathologically as any other disease. "However, oral submucous fibrosis and leukoplakia had 1 common overexpressed gene (PTPN11) and 1 common underexpressed gene (ST7L)." (PMID 40818124, 2025).
liver cancer (1 paper, 2021). An epithelial or non-epithelial malignant neoplasm that arises from the liver. "Studies in liver cancer have shown that ST7L, as the direct target of miR-23b, plays a regulatory role in liver cancer cells and can act as an oncogene." (PMID 34777498, 2021).
Oral leukoplakia (1 paper, 2025). A thickened white patch on the oral mucosa that cannot be rubbed off. "We have identified two common genes, PTPN11 and ST7L, that are commonly deregulated in the precancerous conditions OSF and oral leukoplakia, despite their distinct etiological origins." (PMID 40818124, 2025).
prostate carcinoma (1 paper, 2022). A carcinoma that arises from epithelial cells of the prostate gland. "MiR-331-3p activates Wnt/β-catenin through the suppressor of tumorigenicity 7 protein-like (ST7L) and promotes resistance to chemotherapeutic drugs in prostate cancer." (PMID 35684449, 2022).
tumor (7 papers, 2008 to 2022). "Thus, MIR31HG regulated ST7L expression through sponging miR-575, and acted as tumor suppressor in HCC." (PMID 33334367, 2020). "Further experiments showed that ST7L could abolish the effects of miR-23b and inhibit cell proliferation and metastasis of HCC cells, suggesting that ST7L acted as a tumor-suppressor gene in HCC progression." (PMID 28518144, 2017). "Among the upregulated genes, we identified several oncogenes (Ets2, Fyn, Fos, Rab30 and Src), various tumor markers (Cyp1b1, Gpa33, Cd47, Fam129a, st7l, chka, Lgalsbp, Antxr1 and Ly6a) and other genes related to tumor promotion (Cxcl10, Trim25, Grn, Foxc2, Bmp7 and Irs1)." (PMID 23936067, 2013). "Several genes, such as TMPRSS4, STAR, ST7L, HAS3, FGFR3, CASZ1 and HR, were found to have gene expression changes at the very earliest stages of tumor thickening." (PMID 18442402, 2008). "In addition, in silico modeling has predicted that the tumor suppressors SIAH2 and ST7L are also potential targets of miR-146a." (PMID 24302991, 2013).
cancer (3 papers, 2017 to 2025). A tumor composed of atypical neoplastic, often pleomorphic cells that invade other tissues. "Similar to the ST7 tumor suppressor gene, ST7L can inhibit the proliferation, migration, and invasion of cancer cells." (PMID 36003381, 2022). "Via Targetscan and microRNA.org, we focused on ST7L, which was known to inhibit cell proliferation and invasion of cancer cells, as a potential target gene for miR-23b." (PMID 28518144, 2017). "Conversely, the underexpression of ST7L in precancerous conditions like OSCC may promote apoptosis evasion and progression toward more aggressive cancer forms." (PMID 40818124, 2025). "To explore the molecular mechanisms through which miR-23b and ST7L regulated tumorigenesis and metastasis of HCC, we examined effector molecules of AKT/GSK3β/β-catenin signaling pathway, which was related with tumorigenesis and metastasis of many cancers including HCC." (PMID 28518144, 2017).
ST7L also shares sentences with these, for which no sentence is quoted: cholangiocarcinoma (1 paper); endometriosis (1); gastric cancer (1); gingivitis (1); glioblastoma (1); glioma (1); oral submucous fibrosis (1); Stroke (1).